CTLA4 (cytotoxic T-lymphocyte associated protein 4)
Diseases named in the same sentence as CTLA4 in open-access papers (continued):
Sharing a sentence is not in itself a finding about the gene and the disease.
tumor (continued). "This implies that in the context of bulk RNA-seq, CTLA4 levels function primarily as a surrogate marker for the density of tumor-infiltrating lymphocytes rather than reflecting tumor-intrinsic signaling alone." (PMID 41596281, 2026). "Notably, compared with the PD‐L1− tumor group, the upregulated differentially expressed genes (DEGs) in the CD8‐C2‐Texterm subset from PD‐L1+ tumor group included exhaustion‐related genes such as HAVCR2, CXCL13, PDCD1, TIGIT, LAG3, BATF, GNLY, and CTLA4." (PMID 41194450, 2026). "Currently, anti-TIM-3 drugs are being developed and are in clinical trials, since numerous preclinical studies show that TIM-3 expression on tumor cells leads to the development of resistance to anti-PD-1 or anti-CTLA-4 antibodies, and TIM-3 blocking induces an anti-tumor immune response." (PMID 41596489, 2026). "Additionally, we integrated CleTAC targeting CTLA4 membrane proteins into a CAR construct and evaluated its impact on CAR-T cell functionality and tumor suppressive efficacy using both cellular assays and animal tumor models." (PMID 41328344, 2026). "CTLA-4 inhibitors bind the CTLA-4 molecule with high affinity and block its interaction with the B7 ligand, thereby enabling T cells to recognize and assault tumor cells more effectively." (PMID 40980688, 2025). "Additionally, the ONC-392 trial (NCT04140526) explores an anti-CTLA-4 antibody alone or combined with pembrolizumab in patients with advanced solid tumors, including OSCC, aiming to enhance anti-tumor immunity with reduced toxicity." (PMID 41007256, 2025). "FSTL3 overexpression completely abrogated tumor response to PPC treatment (Prexasertib combined with PD-1 and CTLA-4 blockade) compared to controls, suggesting that FSTL3 may be involved in immunotherapy resistance." (PMID 41029436, 2025). "Collectively, these results indicate that anti-CTLA-4 antibodies reinforce the phenotype of TA-HECs and increase their abundance in the tumor microvasculature by selectively eliminating non-HEV MECA-79− TA-ECs." (PMID 40460830, 2025). "Third, in our in vitro tumor-killing assay, CTLA-4 and PD-1 blockade did not enhance PBMC cytotoxicity, likely due to simplified nature of the experimental system, which cannot reflect complex tumor–immune interactions in vivo." (PMID 41011166, 2025). "Emerging evidence indicates that tumor with elevated TMB generates increased neoantigens, which enhances T cell recognition and correlates with better outcomes following ICIs (such as PD-1/PD-L1 and CTLA-4 inhibitors)." (PMID 41262238, 2025). "Anti-CTLA-4 could be used as an alternative ICI, and tumor induction could also be achieved using other established syngeneic murine tumor cell lines." (PMID 40482036, 2025). "Lactate enhances CTLA-4 expression in the TME by promoting the splicing of CTLA-4 RNA via USP39 in a Foxp3-dependent way, which preserves the functional and phenotypic state of tumor-infiltrating Treg cells." (PMID 40032844, 2025). "This retrospective study aimed to assess the CTLA4 expression in tissue samples from HNSCC that were paraffin-embedded and to assess the expression with various parameters, such as the proportion of the distribution of tumors and tumor grade." (PMID 40861696, 2025). "In the tumor immune landscape, CTLA-4 and PD-1 act as critical negative regulators of T cell activation." (PMID 40725830, 2025). "Preclinical studies in mIDH1-driven tumor models have shown that Ivosidenib restores IFN-γ sensitivity while inducing compensatory immune suppression, including PD-L1 upregulation, increased PD-1 and CTLA4 expression on CD8+ T cells, and Treg recruitment." (PMID 40931345, 2025). "Also, inhibitory signals such as PD-1, CTLA-4, TIM-3, and LAG-3 are released, limiting T cell effector functions in peripheral tissues and tumor microenvironments and contributing to the maintenance of T cell anergy and exhaustion." (PMID 40728994, 2025).
tumor (continued). "The immune checkpoint molecule CTLA-4 demonstrated significant positive correlations with HJURP, VGF and COMP expression (p < 0.05), suggesting potential coordinated regulation of immune evasion and tumor progression pathways." (PMID 40592939, 2025). "Treatment with anti‐PD‐1 and anti‐CTLA‐4 therapy led to the expansion of intratumoral CD69+CD103+CD8+ TRM cells, significantly increasing their cytotoxic capacity in TNBC patients and providing local immune protection against tumor rechallenge." (PMID 39802636, 2025). "PD-1 and CTLA-4 blockade revolutionized the treatment of melanoma and NSCLC, improving survival and offering durable responses by reactivating the immune system’s ability to recognize and attack tumor cells." (PMID 41562047, 2025). "The results also showed that itolizumab significantly enriched PD-1 and CTLA-4 expression on CD8+ T cells but not on NK cells challenged with CD318+ tumor cells." (PMID 40391211, 2025). "The first is a direct enhancement of effector T-cell responses through simple blockade of CTLA-4—‘releasing the brakes’, while the second requires prior elimination of regulatory T cells (TREG) to allow emergence of T-cell-mediated destruction of tumour cells." (PMID 40265076, 2025). "CTLA-4 primarily regulates T-cell activation at the priming stage in tumour-draining lymph nodes involving CD28-mediated T-cell co-stimulation, while PD-1 inhibition primarily occurs at the tumour site during the effector phase." (PMID 41462864, 2025). "Ongoing trials are evaluating whether adding a second checkpoint inhibitor (such as an anti-CTLA-4 antibody) to PD-1 blockade plus chemotherapy can deepen responses, or if novel checkpoints (LAG-3, TIGIT, etc.)might further augment anti-tumor immunity in BTC." (PMID 41007662, 2025). "Preclinical studies demonstrate that TIGIT, LAG-3, and CTLA-4 contribute to T-cell exhaustion through distinct mechanisms, and their co-blockade enhances CD8+ T-cell responses, reduces Treg-mediated immunosuppression, and delays tumor growth in murine models." (PMID 40567374, 2025). "In addition, CTLA4 was highly expressed in the CD4 + FOXP3 T03 subcluster, which only accounted for 16% of cells in tumours." (PMID 39548315, 2025). "Vaccination with p30 peptide and CTLA-4-blocking-only therapy appeared to be unrelated: the efficiency was not enhanced and neither were the frequencies of the tumor-specific clones changed." (PMID 40650228, 2025). "Also, the CTLA-4 molecule expressed by Treg cells prevents the maturation of APC cells and suppresses the activation of CD4+ T cells and CD8+ T cells against tumor antigens." (PMID 40564180, 2025). "By targeting key signaling pathways—PD-1/PD-L1, CTLA-4/CD28, JAK/STAT, PI3K/AKT/mTOR, and MAPK/ERK—it enhances T-cell activation and proliferation and regulates immune checkpoint expression, such as PD-L1 on tumor cells." (PMID 40563651, 2025). "The mRNA expression level of USP35 was significantly increased after anti-PD-1 or anti-CTLA-4 treatment compared with IgG treatment, suggesting USP35 may play a role in tumor immunity." (PMID 40016186, 2025). "Indeed, many studies have confirmed the poor prognostic role of the tumor-infiltrating PDL-1, CTLA-4, PD-1, and FOXP3 immunological markers in BC tissue, however, the role of the circulating levels of these markers is still a debatable issue." (PMID 40108523, 2025). "Downregulation of CTLA4 and ICOS in the LNM MS CD169+ macrophage areas could indicate both immunogenic and immunosuppressive events, possibly affecting anti-tumor T-cell activity in LNM." (PMID 40211433, 2025). "Our data showed for the first time in primary human T cells that deletion of TXNIP led to increased IFN-γ production and expression of T cell activation markers (i.e. CTLA-4 and CD25) and could result in greater tumor cell killing in vitro." (PMID 40260243, 2025).
tumor (continued). "Quantitative analysis of PD-L1, LAG-3, and CTLA-4 expression revealed distinct patterns across the tumors, with a relatively uniform abundance of PD-L1 and LAG-3, but absence of CTLA-4 on tumor-infiltrating T cells." (PMID 40674934, 2025). "Beyond programmed death-1 (PD-1) and cytotoxic T-lymphocyte-associated protein 4 (CTLA-4), novel immune checkpoint receptors (ICRs) play non-redundant roles in suppressing anti-tumor T cell responses." (PMID 41041061, 2025). "Exhausted T cells show increased expression of inhibitory receptors, including CTLA-4 and PD-1, and reduced production of effector cytokines, such as IL-2, tumor necrosis factor (TNF-α), and IFN-γ, further weakening the immune response against the tumor." (PMID 40006624, 2025). "The main advancement in cancer treatment over the past decade has been the introduction of T cell-targeted immunomodulators that block immune checkpoints CTLA-4 and PD1 or PDL1 that are expressed by tumor cells and permits them to avoid T cells’ antitumor activity." (PMID 40361438, 2025). "CTLA-4 KO /KD resulted in increased CAR T cell cytotoxicity and decreased tumor growth." (PMID 41354926, 2025). "However, the combination of all three therapies (anti-PD1 plus anti-CTLA4 plus Prexasertib) or “PPC” was synergistic and significantly improved survival with 80% of the mice tumor-free at the end of the study (p<0.01)." (PMID 41029436, 2025). "Moreover, Tumor, Normal, and Metastasis (TNM) plot analysis from TCGA showed that the expression of KDM1A network genes, including STAT3 and CTLA4, was higher in HNSCC clinical tumors than in normal human tissues." (PMID 40246812, 2025). "TRM cells have the characteristics of long-term tissue residence and rapid response to antigen stimulation, and they highly express various inhibitory checkpoint molecules (such as PD-1, CTLA-4, and LAG-3), playing an important role in anti-tumor immunity such as melanoma." (PMID 40821806, 2025). "Classified as a “cold” tumor, PCa exhibits low T-cell infiltration and an immunosuppressive TME, resulting in limited efficacy of current immune checkpoint inhibitors (ICIs), such as CTLA-4 and PD-1/PD-L1 blockade in mCRPC." (PMID 41561636, 2025). "This inhibition successfully increases T cell activation by allowing CD28 to interact with CD80/CD86 without interference from CTLA-4, resulting in a more robust anti-tumor immune response." (PMID 40739089, 2025). "Notably, dual checkpoint blockade was achieved by co-delivering PD-L1 and CTLA-4 small interfering RNAs (siRNAs) via exosomes, thereby repressing malignant features of CRC cells, restraining tumor growth, and activating tumor immune responses." (PMID 41394216, 2025). "The results indicated that liposomal anti-CTLA-4 not only reduced tumor size but also improved survival rates compared to non-liposomal anti-CTLA-4." (PMID 40277680, 2025). "Hence, we assessed the tumor cell expression of four distinct immune checkpoint ligands; PD-L1, CD80, GAL-9, and PVR, which interact with the clinically relevant receptors PD-1, CTLA-4, TIM3, and TIGIT on T cells." (PMID 40108668, 2025). "Lactate enhances CTLA-4 expression in tumor-infiltrating Treg cells by promoting USP39-mediated RNA splicing in a Foxp3-dependent manner, thereby sustaining Treg function in the tumor microenvironment." (PMID 40535811, 2025). "LNPs can deliver cytokines (e.g., IL-2, IL-12), immune checkpoint inhibitors (e.g., anti-PD-1 or anti-CTLA-4 peptides/mRNA), or adjuvants (e.g., TLR agonists) directly to immune cells or the tumor microenvironment, enhancing the anti-tumor immune response while minimizing systemic toxicity." (PMID 41155952, 2025). "Furthermore, increased expression levels of CTLA4 and PDCD1 were also observed in tumor patients exhibiting hypoxia." (PMID 41419193, 2025).
tumor (continued). "Despite this, most of these tumor-infiltrating MAIT cells display an activated and exhausted phenotype, characterized by increased expression of activation markers (HLA-DR, CD38) and immune checkpoint molecules (PD-1, CTLA-4, TIM-3)." (PMID 40025566, 2025). "After confirmation of tumor growth, cancer-bearing and non-cancer mice received combinatorial treatment of anti-CTLA-4 (two doses per week) and anti-PD-1 (three doses per week) for three weeks." (PMID 40313772, 2025). "The soluble variant sCTLA-4, which is produced and secreted by the CTLA-4 gene via AS in tumor cells, may block CD8+ T cell activation by interfering with the CTLA-4/CD80 signaling pathway." (PMID 40032844, 2025). "Although the cancer blocking system administration of CTLA-4, PD-1/L1 is still significant, non-immunogenic and immunosuppressive tumor microenvironment remains severely hindered." (PMID 40270890, 2025). "While Tex cells were also abundant in the primary tumor tissue, the expression of exhaustion genes (PDCD1, CTLA4, and TIGIT) was notably higher in liver metastasis (LM) tissue, suggesting that T cell functional exhaustion in the metastatic microenvironment contributes to immune evasion." (PMID 40303346, 2025). "Therefore, the activities of anti-CTLA-4 antibodies on tumor-infiltrating Tbet+ICOS+ Th1-like CD4+ T cells and tumor vasculature are both governed by antibody Fc effector function." (PMID 40460830, 2025). "Targeting CTLA-4 with antibodies, such as ipilimumab or tremelimumab, can enhance effector T-cell responses and deplete Tregs in the TME, reducing immunosuppression and enhancing tumor immune surveillance." (PMID 39833954, 2025). "Therefore, CD4+ T cells are important for the remodeling of tumor blood vessels and the increase of TA-HEVs, and they also control the recruitment and functional phenotype of CD8+ T cells during anti-CTLA-4 therapy." (PMID 40460830, 2025). "One further study, however, demonstrated clear anti-CTLA-4-mediated anti-tumour activity that did not require FcgR-mediated destruction of TREG." (PMID 40265076, 2025). "CTLA-4 competes with the costimulatory receptor CD28 for binding B7 molecules (CD80/86) on antigen-presenting cells, while PD-1 inhibits TCR signaling upon engagement with PD-L1 on tumor or immune cells." (PMID 40725830, 2025). "In sharp contrast, treatment with anti‐CTLA4 mAb did not influence control tumors in terms of tumor growth and CD8+ T cell accumulation." (PMID 40230051, 2025). "Notably, tumor-infiltrating CD8+ T cells from SATB1-CAR-T group exhibited 50% lower PD-1, CTLA-4, TIM3, and LAG-3 expression compared to controls, aligning with their exhaustion-resistant phenotype in vitro." (PMID 41372119, 2025). "It has been found that NSCLC patients with high CTLA-4 expression have a poor prognosis, indicating that CTLA-4 may be a potential target for tumor immunotherapy." (PMID 40296912, 2025). "Tumor sections were stained with checkpoint markers: PD1, CTLA4, LAG3, TIGIT, and TIM3." (PMID 40067762, 2025). "The CTLA-4 blockade did not affect the tumor growth or the frequencies of tumor-specific cells but did stimulate Th cell motility." (PMID 40650228, 2025). "Clinical applications of CTLA-4 blockade, alone or in rational combination regimens, are now being investigated across a wide range of tumor types." (PMID 41228293, 2025). "In addition, tumor-specific EphA2 overexpression led to increased PD-1 expression in both CD4+ and CD8+ T cells, while CTLA-4 levels were unchanged." (PMID 40867322, 2025). "There was concurrent and significantly increased expression of the immune checkpoint pathway markers HAVCR2 (TIM-3), CTLA-4, PDCD1 (PD-1), PDCD1LG2 (PD-L1), LAG3, and TIGIT, demonstrating increased immune suppressive signaling from both the tumor and immune cell populations." (PMID 38418892, 2025). "All five mice treated with anti-PD-1/CTLA-4 antibodies plus HDACis showed complete primary tumor elimination without metastasis." (PMID 41024300, 2025).
tumor (continued). "We treated PyMT tumor-bearing mice with a combination of PD1 and CTLA4 blocking antibodies." (PMID 40796746, 2025). "Similarly, dual immune checkpoint blockade, such as targeting PD-1 in combination with CTLA-4, LAG-3, TIM-3, or TIGIT, has shown potential in restoring anti-tumor immunity, particularly in refractory settings." (PMID 40723175, 2025). "The anti-CTLA-4 (aCTLA4) therapy with blocking only antibodies (clone 9D9) of the vaccinated mice did not affect the tumor growth compared to the p30 vaccine-only group." (PMID 40650228, 2025). "Within the TC-TLS, there was a greater abundance of various T cell subsets, including CD8+PD-1+, CD8+PD-1+TIM-3−, CD8+LAG-3−PD-1+TIM-3−, CD8+TIM-3-, CD8+LAG-3−TIM-3−, CD4+FoxP3−, CD4+CTLA-4−, and CD4+PD-L1+ T cells, compared with that in the tumour and stromal regions." (PMID 39901202, 2025). "In addition to PD-1/PD-L1 and CTLA-4, there are other important immune checkpoint molecules such as LAG-3, TIM-3, TIGIT, etc., which also play a key role in tumor immune escape." (PMID 40861450, 2025). "Metformin (Met) reduces tumor-infiltrating Treg (Ti-Treg), especially in the terminally differentiated CD103+KLRG1+ population, and also reduces expression of immune suppressive effector molecules such as CTLA4 and IL-10." (PMID 41246345, 2025). "Additionally, TAMs suppress anti-tumor T-cell responses, enabling immune evasion and tumor growth by secreting anti-inflammatory cytokines (IL-10, TGF-β, PGE2) and inhibiting T-cell activation through checkpoint pathways (PD-1, CTLA-4)." (PMID 40563575, 2025). "C57Bl6 mice bearing GD2+ tumors received 4 or 15 Gy tumor-absorbed doses, determined by individualized dosimetry, with or without dual ICIs (anti-CTLA-4 and anti-PD-L1)." (PMID 42022812, 2025). "Although local or tumor-targeted delivery of CTLA-4 siRNA via NLE-based nanoparticles may reduce systemic exposure, the systemic safety profile of CTLA-4 blockade by siRNA remains a concern." (PMID 40943370, 2025). "The NanoString tumor panel detected in treatment-naïve tumors of the L-TTF2 group higher immune infiltration (e.g., cytotoxic T-cells, B-cells) and checkpoint markers (e.g., PDCD1, CTLA4, TIGIT)." (PMID 40696453, 2025). "Notably, high-risk patients demonstrated enhanced sensitivity to immunotherapy, as indicated by decreased tumor immune dysfunction and exclusion (TIDE) scores and increased expression of the immune checkpoints PD-1 and CTLA4." (PMID 40918134, 2025). "Tumor CTLA4 expression was positively correlated with the prevalence of TILs and TLS in tumors and with a wide range of immune-related gene expression signatures, including the cytotoxicity, interferon gamma, and tumor inflammation signatures." (PMID 40523912, 2025). "By IHC analysis of CTLA-4 expression, positive staining was defined as distinct membranous and/or cytoplasmic brown coloration observed in tumor cells, regardless of intensity." (PMID 40861696, 2025). "In RON−/− mice, the combination of RON inhibition and anti-CTLA-4 did not reduce tumor growth more than anti-CTLA-4 alone." (PMID 40281554, 2025). "Corroborating this observation is the fact that tumor-intrinsic RB activation resulted in no overt changes to Pdcd1 or Ctla4 and even a potential reduction in PD-L1, which would suggest that approaches designed around those targets would prove inconsequential." (PMID 41326426, 2025). "Additionally, we found increases in CTLA-4, TIM-3 and CD137 expression among T cells in the tumor compared to PBMCs, suggesting a complex immunoregulatory network inside the tumor with several possibilities for therapeutical interference." (PMID 39751916, 2025). "Notably, our study revealed a significant correlation between tumor markers (β-HCG and AFP) and the proportion of infiltrating CD4+ and Foxp3+ cells, as well as CTLA-4 expression." (PMID 39958339, 2025).